MYB (MYB proto-oncogene, transcription factor)
Diseases named in the same sentence as MYB in open-access papers (continued):
Sharing a sentence is not in itself a finding about the gene and the disease.
glioma (continued). "More recently, Bandopadhayay et. al. published that 10% (16/172) of their pLGG cohort contained MYB alterations, most commonly as MYB-QKI fusions, including 19/19 (discovery and validation cohorts) angiocentric gliomas." (PMID 32164789, 2020). "The newly established molecular subgroup comprises four distinct entities: 1) Diffuse astrocytoma, MYB or MYBL1-altered; 2) Angiocentric glioma; 3) Polymorphous low-grade neuroepithelial tumor of the young; and 4) Diffuse low-grade glioma, MAPK pathway-altered." (PMID 40861626, 2025). "The diagnosis of angiocentric glioma does not mandatorily require the demonstration of MYB rearrangements." (PMID 38544524, 2024). "The results from a recent report on 33 MYB/MYBL1-altered glioma cases show that a substantial proportion of the cases (at least 13/33) exhibited a rearrangement of the MYB or MYBL1 gene in the absence of a recognizable fusion partner." (PMID 39422766, 2024). "Notably, 5 of 6 patients with altered KMT5B in our study had the same mutation of p.Glu833_Asp835delinsSerProSer, including 3 diffuse astrocytomas, MYB- or MYBL1-altered and 2 diffuse pediatric-type high-grade gliomas, H3-wildtype and IDH-wildtype." (PMID 37214395, 2023). "Among 596 adult patients, 20 patients with pediatric-type glioma were screened, including 6 with diffuse astrocytoma, MYB- or MYBL1-altered, 2 with diffuse midline glioma, H3 K27-altered, and 12 with diffuse pediatric-type high-grade glioma, H3-wildtype and IDH-wildtype." (PMID 37214395, 2023). "In this study, we described and analyzed adult patients with pediatric-type diffuse gliomas, particularly diffuse astrocytoma, MYB- or MYBL1-altered, diffuse midline glioma, H3 K27-altered, and diffuse pediatric-type high-grade glioma, H3-wildtype and IDH-wildtype." (PMID 37214395, 2023). "DNA methylation array profiled the tumour as "methylation class diffuse astrocytoma, MYB or MYBL1-altered subtype B (infratentorial)" and an in-frame MYB::QKI fusion was identified by RNA sequencing, confirming the diagnosis of angiocentric glioma." (PMID 37362245, 2023). "In immunohistochemical examination, compared with angiocentric gliomas, diffuse low-grade glioma, MAPK pathway-altered lacks the characteristic growth pattern around the blood duct center, is EMA spot-positive, and shows MYB variation." (PMID 37920791, 2023). "These were IDH mutant astrocytoma, pilocytic astrocytoma, diffuse astrocytoma, MYB-altered, infant-type hemispheric glioma, CNS embryonal tumor, not elsewhere classified (NEC), MVNT, and PXA." (PMID 36290809, 2022). "The IDH-wildtype astrocytic glioma classified as low-grade glioma MYB/MYBL1 by methylation profiling, was negative for IDH1/IDH2 and BRAF mutations by sequencing analysis and was 1p/19q non-codeleted." (PMID 33941250, 2021). "These tumors do not typically bear alterations found in pediatric gliomas (MYB, FGFR1, BRAF V600E-mutant) either." (PMID 33059718, 2020). "Next-generation sequencing (NGS) of three cases identified mutations in a few genes known to be altered in low-grade gliomas, (e.g., BCOR, BCORL1, ERBB3, MYB, and ATM), but no recurrent mutations were seen." (PMID 31114608, 2019). "Furthermore, overexpression of ZNF143 reversed the inhibitory effects of overexpressed miR-590-3p on glioma cell progression via upregulating ASAP3 and MYB expression." (PMID 31186064, 2019). "Furthermore, ZNF143 promoted the malignant biological behaviors of glioma cells by stimulating ASAP3 and MYB expression." (PMID 31186064, 2019). "Besides EGFR, which is found overexpressed in 40% of gliomas, the genes N-MYC, C-MYC, PDGFR-α, MYB, K-RAS, CDK-4 and MDM2 are the most commonly amplified oncogenes in gliomas." (PMID 18713462, 2008).
glioma (continued). "According to the new WHO CNS5 classification, 4 tumor types have been identified: (i) diffuse astrocytoma, MYB- or MYBL1-altered; (ii) angiocentric glioma; (iii) polymorphic neuroepithelial tumor of the young; (iv) diffuse low-grade, mitogen-activated protein kinase (MAPK) pathway-altered glioma." (PMID 41050069, 2025). "Consequently, the distinction of angiocentric gliomas from what the WHO terms "diffuse astrocytomas, MYB/MYBL1-altered" could be revisited at the time of the next revision of the CNS WHO classification." (PMID 39422766, 2024). "No MYB(L1) fusion or rearrangement was detected in Case 9 by 3 different fusion callers including Arriba, although this case had been classified to the “Diffuse glioma, MYB- or MYBL1-altered” family with maximum confidence scores." (PMID 39422766, 2024). "However, gliomas typically do not express histiocytic markers and exhibit other molecular characteristics, including IDH mutations, ATRX alterations, 1p/19q co-deletions, EGFR amplification, TERT promoter mutations, H3 mutations, MYB/MYBL1 gene structural mutations, and FGFR1 mutations, etc." (PMID 40231251, 2025). "Alterations in MYB, MYBL were recently reported to characterize diffuse grade II, but not grade I, gliomas." (PMID 35574540, 2022). "Rearrangements involving MYB or MYBL1, but not QK1, were observed in some low-grade gliomas, mostly pertaining to the diffuse astrocytoma group." (PMID 30279357, 2018). "Of the 147 non-angiocentric gliomas analyzed by WGS or RNA-seq, none exhibited MYB-QKI fusions, suggesting that this fusion might be a specific target for AG." (PMID 39479357, 2024). "MiR-590-3p could bind to the ZNF143 3′ UTR and repress the expression of ASAP3 and MYB by negative modulation of ZNF143, thereby hindering the malignant progression of glioma cells." (PMID 31186064, 2019).
diffuse astrocytoma (49 papers, 2016 to 2025). A low-grade (WHO grade II) astrocytic neoplasm. "MYB or MYBL1 alterations represent driver mutations that occur early in the tumorigenesis process of diffuse astrocytoma, MYB or MYBL1-altered, resulting in the presence of this abnormality in nearly all tumor cells." (PMID 40668344, 2025). "The MYB/MYBL1 alterations are associated with diffuse astrocytoma, while the MYB-QKI fusion is highly relevant to AG." (PMID 37920791, 2023). "Diffuse astrocytoma, MYB- or MYBL1-altered, is a diffusely infiltrative astrocytic neoplasm that lacks histomorphological features indicative of an anaplastic nature." (PMID 40861626, 2025). "The DNA methylation profile of this tumor closely aligns with that of diffuse astrocytoma, MYB- or MYBL1-altered." (PMID 40861626, 2025). "In most cases of diffuse astrocytoma, MYB- or MYBL1-altered form masses in the supratentorial region, although brainstem involvement occurs only exceptionally." (PMID 40668344, 2025). "“MYB- or MYBL1-altered diffuse astrocytoma” is a rare entity defined by a canonical fusion event of MYB- or MYB1L, with the most common partner genes PCDHGA1, MMP16, and MAML2." (PMID 40392954, 2025). "Diffuse astrocytoma, MYB- or MYBL1-altered is an infiltrative neoplasm of astroglial origin, characterized by uniform cellular morphology and specific genetic modifications in either the MYB or MYBL1 genes." (PMID 40668344, 2025). "Diffuse astrocytoma, MYB- or MYBL1-altered, is classified as CNS WHO grade 1 with favorable prognosis, with a reported 5-year event-free survival rate of 100% in cases with near-total resection." (PMID 40668344, 2025). "This histological overlap between AG and diffuse astrocytoma, MYB- or MYBL1-altered pose challenge in differential diagnosis." (PMID 40668344, 2025). "The primary therapeutic approach for diffuse astrocytoma, MYB- or MYBL1-altered, is maximal safe surgical resection." (PMID 40668344, 2025). "Diffuse astrocytoma, MYB- or MYBL1-altered is a diffusely infiltrative astroglial neoplasm composed of monomorphic cells and characterized by genetic alterations regarding MYB or MYBL1 genes." (PMID 38544524, 2024). "IHC: Similar to diffuse astrocytoma, MYB/MYBL1 altered, along with a few cases showing focal epithelial membrane antigen (EMA) positivity in a dot-like pattern representing epithelioid elements." (PMID 39440342, 2024). "Histologically, diffuse astrocytoma, MYB- or MYBL1-altered typically shows low-to-moderate cellularity and is composed of well-differentiated neoplastic astrocytes with small, round-to-ovoid nuclei, diffusely permeating neuropil." (PMID 38544524, 2024). "Reviewing the available molecular data, these cases presumably include MAPK altered pediatric-type diffuse low-grade gliomas °2 and MAPK altered and MYB-/MYBL-altered pediatric-type diffuse astrocytoma °2." (PMID 38580878, 2024). "Diffuse astrocytoma, altered by MYB/MYBL1 (MYB proto-oncogene like 1), is a cerebral tumor predominantly located in the cortical or subcortical areas." (PMID 39440342, 2024). "This category includes the following tumors: diffuse astrocytoma, MYB/MYBL1 altered, angiocentric glioma, polymorphous low-grade neuroepithelial tumor of the young (PLNTY), and diffuse low-grade glioma, mitogen-activated protein kinase (MAPK) pathway altered." (PMID 39440342, 2024). "Diffuse astrocytoma, MYB- or MYBL1-altered shows a benign clinical behavior, even though the available outcome data are limited due to its rarity." (PMID 38544524, 2024). "Two morphological subtypes are recognised: angiocentric glioma and diffuse astrocytoma, MYB- or MYBL1-altered." (PMID 39294363, 2024). "Diffuse astrocytoma, MYB- or MYBL1-altered is rare, accounting for only 2% of pediatric low-grade gliomas." (PMID 38544524, 2024).
diffuse astrocytoma (continued). "The remaining IDH-wildtype anaplastic astrocytomas (13/39) and IDH-wildtype diffuse astrocytomas (7/26) were reclassified as pediatric-type diffuse astrocytoma, MYB- or MYBL1-altered or high-grade diffuse glioma, H3- and IDH-wildtype." (PMID 36998447, 2023). "In contrast, fewer patients (3/6, 50%) with diffuse astrocytoma, MYB- or MYBL1-altered, showed enhancement." (PMID 37214395, 2023). "pLGGs include diffuse astrocytoma, MYB- or MYBL1-altered; angiocentric glioma; polymorphous low-grade neuroepithelial tumor of the young; and diffuse low-grade glioma, MAPK pathway-altered." (PMID 37214395, 2023). "In diffuse astrocytoma, MYB- or MYBL1 altered, large cysts are commonly reported, however, in our study, cyst was only observed in one case, albeit with the largest cyst diameter among all samples." (PMID 37214395, 2023). "Two newly defined CNS WHO grade 1 entities in this category are diffuse astrocytoma, MYB- or MYBL1-altered, and polymorphous low-grade neuroepithelial tumor of the young (PLNTY)." (PMID 36617415, 2023). "Patients with diffuse astrocytoma, MYB- or MYBL1-altered are mostly diagnosed with drug-resistant seizures, previous study suggested that 81% of these patients develop epilepsy in childhood and the median age of seizure onset is 10 years." (PMID 37214395, 2023). "Under “pediatric type diffuse low-grade gliomas,” three new tumor types are introduced: “diffuse astrocytoma, MYB or MYBL1-altered”; “polymorphous low-grade neuroepithelial tumor of the young (PLNTY)”; and “diffuse low-grade glioma-MAPK altered”." (PMID 38137148, 2023). "The mean maximum tumor diameter was 4.19, 4.96, and 4.17 cm for diffuse astrocytoma, MYB- or MYBL1-altered, diffuse midline glioma, H3 K27-altered, and diffuse pediatric-type high-grade glioma, H3-wildtype and IDH-wildtype, respectively." (PMID 37214395, 2023). "Diffuse astrocytoma, MYB- or MYBL1-altered accounts for approximately 2% of all pediatric low-grade gliomas composed of monomorphic cells." (PMID 37214395, 2023). "Diffuse astrocytomas are low-grade diffusely growing neoplasms, MYB-altered or MYBL1-altered, and commonly arise within the cortex or subcortex of the temporal and frontal lobes." (PMID 37462746, 2023). "Just like diffuse astrocytomas with MYB or MYBL1 alteration, angiocentric gliomas infiltrate adjacent brain structures diffusely, although they can appear as well-demarcated lesions in MRI." (PMID 36941392, 2023). "Diffuse astrocytoma with alterations of MYB/MYBL1 is a diffuse, infiltrating tumor composed of astrocytic cells." (PMID 37920791, 2023). "In contrast, the mOS of diffuse astrocytoma, MYB- or MYBL1-altered, was 46.3 months, suggesting that adult patients with high-grade pediatric-type diffuse glioma are less likely to experience longer survival and better prognosis." (PMID 37214395, 2023). "Diffuse astrocytoma, MYB- or MYBL1-altered, is a diffuse infiltrative neoplasm composed of astrocytoid cells that exhibit histological morphology indistinguishable from conventional astrocytomas." (PMID 37920791, 2023). "This reference cohort consisted of Ganglioglioma (LGG, GG), Dysembryoplastic Neuroepithelial Tumours (LGG, DNT), Pleomorphic Xantoastrocytoma (LGG, PXA), and diffuse astrocytoma, MYB- or MYB-L1 altered (LGG, MYB)." (PMID 36973520, 2023). "Especially in adolescents and young adults, diffuse astrocytomas, MYB-altered or MYBL1-altered, have to be distinguished from IDH-wildtype and IDH-mutated diffuse gliomas." (PMID 37462746, 2023). "Patients with diffuse astrocytoma,MYB- orMYBL1-altered; present with drug-resistant epileptic seizures." (PMID 35969220, 2022). "Based on histomorphology and molecular profile, we detected a diffuse astrocytoma, MYB or MYBL1-altered with MYBL1:MMP16-fusion." (PMID 35727368, 2022). "For example, diffuse astrocytoma, MYB- or MYBL1-altered belong to the family of pediatric-type diffuse low-grade gliomas and are classified as CNS WHO grade 1." (PMID 36425564, 2022).
diffuse astrocytoma (continued). "The “non‐specific/diffuse DNTs” subgroup encompasses various recently described histomolecular entities, such as PLNTY and diffuse astrocytoma, MYB or MYBL1 altered." (PMID 35836307, 2022). "Then, there are three subclasses of diffuse astrocytoma, MYB or MYBL1-altered, whose methylation profiles are most similar to paediatric MYB/MYBL1-altered diffuse astrocytomas and angiocentric gliomas." (PMID 36428772, 2022). "Contrarily to specific forms, “non‐specific/diffuse DNTs” corresponded to a heterogeneous molecular group encompassing newly described distinct histo‐molecular tumours as PLNTY or diffuse astrocytoma, MYB or MYBL1‐altered." (PMID 35836307, 2022). "The molecular alterations of these “pediatric-type” grade II diffuse astrocytomas were recently described and concerned the BRAF p.V600E mutation, FGFR1 alterations or MYB or MYBL1 rearrangement." (PMID 32771057, 2020). "The authors concluded that 60% of diffuse astrocytomas displayed MYB up-regulation at the protein level, but were unable to identify a unifying genetic event responsible for the observation." (PMID 32164789, 2020). "Work investigating the genetics of uncommon low-grade neuroepithelial tumors showed that 87% and 41% of angiocentric glioma and diffuse astrocytoma, respectively, harbored MYB alterations." (PMID 32164789, 2020). "Various genetic alterations have been identified in diffuse astrocytomas, including BRAFV600E mutations, intragenic duplication of FGFR1, structural alterations of the MYB oncogene and gene fusions involving FGFR1, FGFR3, MYB and MYBL1." (PMID 27229157, 2016). "In cases where such genetic alterations are not detectable, a distinct DNA methylation profile characteristic of diffuse astrocytoma, MYB- or MYBL1-altered, may be sufficient to establish the diagnosis." (PMID 40861626, 2025). "pDLGG includes four tumor types, namely, diffuse astrocytoma, MYB- or MYBL1-altered; angiocentric glioma; polymorphous low-grade neuroepithelial tumor of the young (PLNTY); and diffuse low-grade glioma, MAPK pathway-altered, three types of which are newly recognized tumor types." (PMID 37920791, 2023). "The spectrum of long-term low-grade epilepsy-associated brain tumors is expanding rapidly and, in addition to DNTs, includes diffuse astrocytoma MYB or MYBL1-altered polymorphous low-grade neuroepithelial tumor of the young (PLNTY), diffuse low-grade glioma, MAPK pathway-altered tumor, and so on." (PMID 37525202, 2023). "After removing missing data, 6 patients with diffuse astrocytoma, MYB- or MYBL1-altered, 1 with diffuse midline glioma, H3 K27-altered, and 7 with diffuse pediatric-type high-grade glioma, H3-wildtype and IDH-wildtype were included in the analysis, and representative radiological images are shown." (PMID 37214395, 2023). "The prognosis of diffuse astrocytoma with alterations of MYB/MYBL1 is generally excellent." (PMID 37920791, 2023). "Diffuse astrocytoma, MYB or MYBL1-altered, shows astrocytic cells in a fine bubbly neuropil." (PMID 37525202, 2023). "These include diffuse astrocytoma, MYB- or MYBL1-altered; diffuse low-grade glioma, MAPK pathway-altered; polymorphous low-grade neuroepithelial tumor of the young (BRAF mutations and FGFR2 fusions); and infant-type hemispheric glioma (alterations in NTRK, ROS1, ALK, or MET)." (PMID 37509316, 2023). "Interestingly, 77% of IDGs demonstrated MYM/MYBL1 alterations, and all (100%) were IDH-wild-type, which are closely related to pediatric MYB/MYBL1-altered diffuse astrocytomas, according to the WHO fifth edition of CNS tumor classification." (PMID 36699536, 2022). "Moreover, WHO CNS5 classifies diffuse astrocytomas, MYB- or MYBL1-altered as CNS WHO grade 1." (PMID 34638714, 2021). "There is a trend toward collectively managing AG and diffuse astrocytoma, MYB- or MYBL1-alterations within the same spectrum, under the broader classification of MYB- or MYBL1-altered pLGGs." (PMID 40668344, 2025).
diffuse astrocytoma (continued). "Both diffuse astrocytoma, MYB- or MYBL1-altered and angiocentric glioma (AG) are pLGGs that harbor MYB or MYBL1 alterations." (PMID 40668344, 2025). "Conversely, Diffuse astrocytoma, MYB- or MYBL1-altered tumors show structural variations that result in a fusion involving more commonly MYBL1, although MYB alterations also occur." (PMID 39422766, 2024). "In 2021, the World Health Organization updated their CNS tumor classification to include two categories of these pLGGs: angiocentric glioma with MYB-QKI fusions and diffuse astrocytoma with various MYB/MYBL1 alterations." (PMID 38137148, 2023). "Unlike other pediatric low-grade gliomas (pLGGs), diffuse astrocytoma, MYB- or MYBL1-altered, typically lacks common therapeutic targets such as BRAF mutations." (PMID 40668344, 2025). "FGFR1, NTRK2, MYB, and MYBL1 rearrangements: Among patients with diffuse astrocytomas who had testing for rearrangements of FGFR1 (n = 5), NTRK2 (n = 4), MYB (n = 2), or MYBL1 (n = 1) performed on both paired surgical specimens, results remained negative in all pairs, with no acquisition or loss." (PMID 33153497, 2020). "No MYB or MYBL1 rearrangements were identified in any of the cases, suggesting that gangliogliomas are genetically distinct from the majority of angiocentric gliomas and pediatric IDH-wildtype diffuse astrocytomas." (PMID 29880043, 2018).